NTRK2 (neurotrophic receptor tyrosine kinase 2)
Diseases named in the same sentence as NTRK2 in open-access papers (continued):
Sharing a sentence is not in itself a finding about the gene and the disease.
Stroke (56 papers, 2011 to 2026). Sudden impairment of blood flow to a part of the brain due to occlusion or rupture of an artery to the brain. "Of special interest, are proteins such as FBXO7 and NTRK2, which were downexpressed in stroke, but overexpressed after treatment with Ngb-NPs; and ATX2L, which was overexpressed only under the effect of Ngb." (PMID 35008673, 2021). "Particularly, the ischemic lesion induced the underexpression of FBXO7 and NTRK2, although when stroke animals were treated with Ngb-NPs, both proteins underwent a strong recovery and even overexpression." (PMID 35008673, 2021). "Similarly, interference with BDNF/NT-3 growth factors receptor (NTRK2) signalling can impact infarct size, neurogenesis and outcome after stroke in vivo." (PMID 36418382, 2022). "Specifically, when comparing MCAO vs. sham, proteins FBXO7, WIPI2, NTRK2, A0A0G2JY03, and ITGB8 appeared clearly underexpressed, whereas MAP1a and CPQ were overexpressed, indicating a clear effect of the stroke (MCAO injury) on the individuals." (PMID 35008673, 2021). "We confirm this strong influence of post-stroke training (both voluntary and FAU) on basal neuronal plasticity mechanisms, and find up regulation of NTRK2, NMDA 2a receptor, or MAP1b." (PMID 24528872, 2014). "NTRK2 (high affinity nerve growth factor receptor) is a receptor of BDNF that is also involved in neurogenesis and neuronal plasticity; this protein has been related to stroke throughout the pathway BDNF-TrKBPI3K/Akt." (PMID 35008673, 2021). "Finally, in the comparison between MCAO-Ngb and MCAO, which demonstrates the effects of the treatment with Ngb-NPs in animals submitted to stroke, the most evident changes involved overexpression of ATXN2l, FBXO7, and NTRK2." (PMID 35008673, 2021).
lung carcinoma (36 papers, 2010 to 2025). "Our finding that NTRK2 activates PI3K/mTOR signaling is consistent with recent studies that NTRK2 promotes lung cancer and chondrosarcoma survival and metastasis by activating PI3K/AKT signaling." (PMID 27672444, 2016). "Five of these lung cancer patients had novel NTRK2 fusions with intronic breakpoints that would likely have been missed if using a DNA NGS targeted panel, potentially leading to first-line immune checkpoint inhibitor therapy with decreased efficacy in the presence of a co-occurring oncogenic driver." (PMID 40385986, 2025). "RNA sequencing revealed a number of genes differentially expressed in lung tumors lacking Akt2 and five of these genes, Actc1, Bpifa1, Mmp2, Ntrk2, and Scgb3a2 have been implicated in human lung cancer." (PMID 26654940, 2016). "Nevertheless, there were few investigations about the relationship between NTRK2 and lung cancer, particularly LUAD, so the effects and mechanisms of NTRK2 in LUAD require further research." (PMID 31245181, 2019). "However, the detailed function of NTRK2 in lung cancer, especially in lung adenocarcinoma (LUAD), is still not fully understood." (PMID 31245181, 2019). "Moreover, a study performed on 60 patients with non-microcellular lung cancer, found that NTRK2 expression was 66.7%and remarkably, a statistically significant correlation between NTRK2 gene expression and TNM stage and secondary lymphatic determinations was also observed." (PMID 35860155, 2022).
glioblastoma (34 papers, 2010 to 2025). The most malignant astrocytic tumor (WHO grade IV). "Our data are in agreement with those showing that IDH wild-type glioblastoma with overexpression of NTRK2 is associated with better OS (p = 0.049; HR: 0.66)." (PMID 30991699, 2019). "Patient #12, a 54-year-old male diagnosed with glioblastoma (GBM) with the BCR::NTRK2 fusion, PTEN mutation, homozygous deletion of CDKN2A/2B, and TERTp mutation (C228T), refused adjuvant therapy and received palliative care, resulting in death 13 months post-surgery." (PMID 39014476, 2024). "One glioblastoma patient with a NACC2::NTRK2 fusion was still in remission two years after treatment with conventional therapy." (PMID 41331048, 2025). "Mice bearing orthotopic xenografts of NTRK2-KO DIPG in the brainstem or NTRK2-KO paediatric cortical glioblastoma in the frontal cortex exhibited a marked increase in overall survival compared with littermate controls xenografted with NTRK2 wild-type cells." (PMID 37914930, 2023). "Two of these cases (18%) (liponeurocytoma, glioblastoma) with Pan-Trk expression (diffuse, partial) were found to have NTRK2-fusions (SLC O 5A1-NTRK2, AGBL4-NTRK2, BEND5-NTRK2) and these cases were adult." (PMID 35295612, 2022). "For example, among brain tumors, glioblastoma, pilocytic astrocytoma, and pontine glioma can show gene fusions involving NTRK2 or NTRK3." (PMID 32906676, 2020). "Furthermore, we compared the (ex4:ex13) fusion identified in pilocytic astrocytoma with the (ex4:ex15) fusion identified in pediatric glioblastoma, which differ by the presence or absence of NTRK2 exons 13 and 14 that encode the TM (transmembrane) helix." (PMID 38935636, 2024). "Furthermore, NTRK2 was associated with peroxisome proliferator–activated receptor α (PPARα), which was overexpressed and correlated with a good prognosis in IDH wild-type primary glioblastoma." (PMID 30991699, 2019). "An earlier study showed that immature dentate granule cells (DGCs) emit brain-derived neurotrophic factor (BDNF) and that glioblastoma stem cells (GSCs) express neurotrophic receptor kinase 2 (NTRK2), also known as TrkB, an appropriate receptor for BDNF." (PMID 36865549, 2023). "The other two positively expressed cases (liponeurocytoma and glioblastoma) were found to have NTRK2-fusions (SLC O 5A1-NTRK2, AGBL4-NTRK2, BEND5-NTRK2)." (PMID 35295612, 2022). "The alterations in FGFR4, KIT, and PEG3 were correlated with a short OS in astrocytoma, alterations in CDK4, FUBP1, and NTRK2 were correlated with a short OS in oligodendroglioma, and alterations in CDK4, CIC, FGFR3, and KMT5B were correlated with a short OS in glioblastoma." (PMID 36998447, 2023). "However, APOA2, NTRK2, and FGA are oncogenes in PDAC, glioblastoma, and gastric cancer." (PMID 31143705, 2019). "The relationship between IDH status and NTRK2 or CHI3L1 has not yet been studied in grade II and III tumors and was only reported for glioblastoma." (PMID 30991699, 2019).
breast carcinoma (32 papers, 2008 to 2025). "It has been reported that NTRK2 has significant associations with the side effects of breast cancer patients after chemotherapy." (PMID 35383130, 2022). "SOX2 can also affect NTRK2 expression, and NTRK2 is essential for tumor migration, potentially by influencing E-cad levels in a manner similar to breast cancer." (PMID 40133476, 2025). "The fusion type of NTRK2 is specifically decreased in breast cancer while NTRK2 itself is closely related to breast cancer; it is related to sleep disorders after surgery and increases the incidence of side effects after chemotherapy." (PMID 35383130, 2022). "Our results demonstrated that hsa_circ_0006014 promotes breast cancer progression by sponging miR-885-3p to regulate the NTRK2/PIK3CA/AKT axis." (PMID 35383130, 2022). "The expression of NTRK2 was reported to be down-regulated in patients with breast cancer with a poor prognosis." (PMID 31034520, 2019). "Surprisingly, a recent report revealed that NTRK2 inhibits KEAP1 expression in breast cancer cells and is involved in cancer proliferation, survival, and metastasis." (PMID 29306329, 2018). "Interestingly, from a clinical perspective, stratifying patients based on either the expression levels of NTRK2 (TRKB) or FOXO1 is predictive of a good prognosis (overall survival) in breast cancer, similar to prognosis based on PR expression." (PMID 36034422, 2022). "Our study indicates that circ_6014 could sponge miR-885-3p and thus regulate the NTRK2/PIK3/AKT pathway in breast cancer, which we hope could be a new therapeutic strategy for breast cancer in the future." (PMID 35383130, 2022). "Therefore, our results demonstrated that circ_6014 can sponge miR-885-3p to regulate the NTRK2 and PIK3/AKT pathways in breast cancer." (PMID 35383130, 2022).
glaucoma (30 papers, 2010 to 2025). Increased pressure in the eyeball due to obstruction of the outflow of aqueous humor. "Other central nodes in this network have already been associated with glaucoma, such as NTRK2 (the neurotrophic receptor tyrosine kinase 2, alias TRKB), which showed the highest centrality values inside the network." (PMID 39458974, 2024).
mood disorder (30 papers, 2013 to 2025). A cognitive disorder a disturbance in which the person's mood is hypothesized to be the main underlying feature. "Genetic studies have revealed that NTRK2 is associated with the treatment response to mood stabilizers in BD and suicidal behavior in mood disorders." (PMID 33875800, 2021). "As to NTRK2 gene polymorphisms, previous studies have shown that NTRK2 gene polymorphisms rs2769605, rs1387923, and rs1565445 were associated with mood disorders or antidepressants response." (PMID 24069289, 2013). "Previous studies have demonstrated that three polymorphisms in NTRK2 gene (rs2769605, rs1387923, and rs1565445) were associated with mood disorders." (PMID 24069289, 2013). "Also, an association study found evidence of NTRK2 linked to childhood-onset mood disorders." (PMID 28628658, 2017). "NTRK2, also known as TrkB, encodes a BDNF receptor and has been one of the prime targets in mood disorders." (PMID 33875800, 2021).
cognitive decline (28 papers, 2014 to 2025). "Genes involved in neuronal postsynaptic density were enriched among DMRs associated with the rate of cognitive decline as measured by mPACCtrailsB, and this enrichment was driven by DMRs annotated to BNIP3, NTRK2, and BAIAP2." (PMID 34654479, 2021).
Huntington disease (23 papers, 2013 to 2025). Huntington disease (HD) is a rare neurodegenerative disorder of the central nervous system characterized by unwanted choreatic movements, behavioral and psychiatric disturbances and dementia. "Another circRNA is hosted by NTRK2, a gene that was associated with synaptic dysfunction in Huntington’s disease and neuronal differentiation and plasticity in hippocampus." (PMID 28842720, 2017). "Furthermore, it was shown that in Huntington’s disease patients’ neurons, the retrograde transport of NTRK2, and therefore BDNF signaling, is impaired by mutated HTT." (PMID 32151030, 2020). "Although further investigation is warranted, these results suggest that NTRK2 has protective potential in Huntington’s disease, especially in individuals with certain genotypes." (PMID 29932126, 2018).
autism (22 papers, 2011 to 2026). Persistent deficits in social interaction and communication and interaction as well as a markedly restricted repertoire of activity and interest as well as repetitive patterns of behavior. "In this context, a genetic study of 469 trio families reported that genetic polymorphisms of NTRK2 are linked to autism pathogenesis." (PMID 38994948, 2024). "This study also showed that BDNF levels were significantly increased in children with autism relative to that in controls, supporting a role of NTRK2/BDNF signaling as a susceptibility factor for the disorder." (PMID 23697635, 2013). "Its role in ASD is implicated by genetic association analysis of 146 children with autism and 50 typically developing controls which identified six SNPs and multiple haplotypes in the NTRK2 gene." (PMID 23697635, 2013). "Interestingly, TrkB involvement in autism pathogenesis is substantiated by the finding of an association between trkB (nTrk2) gene variants and autism." (PMID 25627160, 2015). "There is evidence that NTRK2 gene is a susceptibility factor for autism and a disruption of the BDNF/TrkB signaling pathway is associated with autism." (PMID 41245836, 2025). "TrkB has been genetically proven to play an important role in hippocampal synaptic plasticity and learning and has been proposed as a susceptibility factor for autism, suggesting that NTRK2 duplication in the patient’s mother may have influenced both feeding difficulties and behavioral phenotype." (PMID 26425634, 2015). "Interestingly, we also found a 30-fold decrease in the expression of NTRK2, the BDNF receptor gene, in the astrocytes of patients with autism." (PMID 38994948, 2024). "Interestingly, the expression of NTRK2 (a receptor for BDNF), with almost 3-fold greater expression in astrocytes vs. neurons, exhibited a 30-fold decrease in the astrocytes of patients with autism vs. controls (p = 0.01), but not in neurons or NSCs." (PMID 38994948, 2024).
ovarian carcinoma (22 papers, 2010 to 2025). A malignant neoplasm originating from the surface ovarian epithelium. "For example, in ovarian cancer cells, the interaction between EGFR and NTRK2 enhances the migration and proliferation of ovarian cancer cells by increasing the phosphorylation of AKT." (PMID 38791682, 2024). "Elevated BDNF/NGF levels promote innervation via neurotrophic receptor tyrosine kinase 2 (TrkB) receptors, and overexpression of TrkB is related to shorter survival with ovarian cancer patients." (PMID 36707854, 2023).
colorectal cancer (20 papers, 2009 to 2025). A primary or metastatic malignant neoplasm that affects the colon or rectum. "Likewise, neurotrophic receptor tyrosine kinase 2 (NTRK2) is associated with poor prognosis in lung and colorectal cancer." (PMID 36064939, 2022). "In this study, we identified PAPSS2, TUBG2, NTRK2, B4GALT1 and OSMR as genes harboring cancer-specific promoter methylation in human colorectal cancer." (PMID 19662090, 2009). "Furthermore, Cubisbel uniquely upregulated genes such as NTRK2 in SW480 cells, which has been previously suggested to act as a tumor suppressor in colorectal cancer." (PMID 37934338, 2024). "Overall, the most frequently mutated drug target genes were BRAF for thyroid cancer, FGFR2 for endometrial cancer, EGFR for brain tumors, MGMT for colorectal cancer, FGFR2 and FGFR3 for bladder cancer, NTRK3 for non-small cell lung cancer and NTRK2, FGFR2, EGFR for stomach cancer." (PMID 32111026, 2020).
gastric cancer (19 papers, 2009 to 2025). A primary or metastatic malignant neoplasm involving the stomach. "In Hu’s study, NTRK2 is an oncogene related to microRNA-22 regulation in human gastric cancer cell line." (PMID 39351154, 2024). "In a study conducted on MKN-28 and SNU-719 Gastric Cancer (GC) cells, it was found that NTRK2 is aberrantly expressed in GC cell lines compared to normal gastric cells." (PMID 40061872, 2025).
endometrial cancer (18 papers, 2013 to 2024). Primary or metastatic malignant neoplasm involving the endometrium (mucous membrane that lines the endometrial cavity). "miR-204 is reported to act as a tumor suppressor in a variety of cancers through different mechanisms including down-regulation of Bcl-2, NTRK2 in neuroblastoma cancer and suppression of invasion in endometrial cancer mediated by FOXC1 regulation." (PMID 24025188, 2013). "miR-204 also influences NTRK2 gene expression in neuroblastoma cancer and FOXC1 gene in invasive endometrial cancer." (PMID 26126974, 2015).
lung adenocarcinoma (18 papers, 2011 to 2024). A carcinoma that arises from the lung and is characterized by the presence of malignant glandular epithelial cells. "Ten cohorts listed NTRK2 fusions exclusively which were either brain/CNS tumours or lung adenocarcinoma." (PMID 36914665, 2023). "NTRK2 and its fusions are of interest in different tumors, i.e. secretory carcinoma of the salivary gland and lung adenocarcinoma, because they can be targeted by specific inhibitors." (PMID 36564761, 2022). "In human lung adenocarcinoma cell lines and a mouse model of adenocarcinoma, Ntrk2 promoted cell migration and tumor cell metastasis." (PMID 26654940, 2016). "As for the other reference genes such as ROS1, HER2, RET, MET, NTRK1, NTRK2, and NTRK3, our study did not identify mutations in these genes in patients with lung adenocarcinoma." (PMID 38828424, 2024). "Furthermore, 23 newly NTRK1, NTRK2, and NTRK3 gene fusions were identified across different tumor types, including lung adenocarcinomas." (PMID 36289793, 2022).
bipolar disorder (14 papers, 2011 to 2025). A disorder of the brain that causes unusual shifts in mood, energy, activity levels and the ability to carry out day-to-day tasks. "While our findings suggest that astrocyte’s reduced growth rate may be due to the decreased expression of NTRK2 in these cells, its reduced expression is likely due to DNA hypermethylation, as shown in the postmortem brains of patients with bipolar disorder." (PMID 38994948, 2024).
prostate carcinoma (13 papers, 2015 to 2024). A carcinoma that arises from epithelial cells of the prostate gland. "NTRK2 has also been shown to be hypermethylated in colon cancers as well as prostate cancer cell lines and cancers." (PMID 27795744, 2016). "In prostate cancer, the development of NGF/NTRK1 or BDNF/NTRK2 autocrine signaling pathways is an escape mechanism, from both the androgen control and the paracrine dependence of stromal cells produced neurotrophins." (PMID 29904026, 2018).
astrocytoma (10 papers, 2007 to 2024). "One anaplastic astrocytoma with CLIP2:NTRK2 fusion was classified as anaplastic pilocytic astrocytoma (CS 0.62), currently also known as high-grade astrocytoma with piloid features (HGAP)." (PMID 36163281, 2022). "In grade 2–3 astrocytoma, variations in FGFR4, KIT, NTRK2, and positive immunohistochemistry for ATRX and EGFR showed statistically significant results in univariate survival analysis." (PMID 38970209, 2024).
colon cancer (10 papers, 2009 to 2024). "Neurotrophin tyrosine kinase receptor type 2 (NTRK2) and urokinase type plasminogen activator (PLAU) were also included because no reports on methylation of the two genes in colon cancer have been published yet." (PMID 19662090, 2009).
melanoma (10 papers, 2011 to 2024). A malignant, usually aggressive tumor composed of atypical, neoplastic melanocytes. "Based on our previous results that implicated RKIP on the migration capability of melanoma cells, we made use of RKIP overexpression to analyze the effect on ZEB1, NTRK2, and THY-1 transcription." (PMID 32503139, 2020). "Among 751 cases, they identified three cutaneous primary melanomas (3/395; 0.8%) and one mucosal/paramucosal melanoma (1/113; 0.9%) harbouring NTRK1 or NTRK2 gene fusions." (PMID 31738427, 2019). "In differentiation-supported conditions, TAFH RNAi-treated melanoma cells started to express chondrogenic-specific SOX9, NKX3.2 and RUNX2; adipogenic PPARG; and neurogenic NTRK2, NF-M and SYP mRNAs at 48 h post-stimulation of differentiation." (PMID 27499390, 2016). "Consistently, no transplanted organoid cells corresponded to SOX2+ NTRK2+ neural precursors or PMEL+ melanoma-like cells." (PMID 31784515, 2019).
alcoholism (9 papers, 2015 to 2025). "The cluster of DRD2 and GRIN2B share the alcoholism pathway with NTRK2 (rs1439047) and have the same pathways of neuroactive ligand–receptor interaction and dopaminergic synapse as does DRD3 (rs2134655)." (PMID 28512340, 2017). "Thus, the mechanism underlying ALDH1A1-related alcoholism is different from the gene cluster of DRD2, DRD3, GRIN2B, and NTRK2, which is directly involved in behavioural rewarding effects of alcohol consumption." (PMID 28512340, 2017). "Importantly, we are the first to report SNPs associated with unequal age-of-onset distributions for susceptible cases to alcoholism [rs172677 on GRIN2B (p = 0.013), rs1439047 on NTRK2 (p = 0.005), rs63319 on ALDH1A1 (p = 0.033), and rs1079597 on DRD2 (p = 0.028)]." (PMID 28512340, 2017). "Pathway analysis shows that NTRK2 is mainly involved in the PI3K-Akt signaling pathway, Ras signaling pathway, alcoholism, MAPK signaling pathway, and neurotrophin signaling pathway." (PMID 39769319, 2024).